TBC1D15 (TBC1 domain family member 15)
Description:
Acts as a GTPase activating protein for RAB7A. Does not act on RAB4, RAB5 or RAB6 (By similarity).
Synonyms: Rab7-GAP; FLJ12085; DKFZp761D0223
Tractability: Antibody: its Gene Ontology location is reachable by antibodies, with medium confidence. PROTAC: ubiquitination databases record sites on it; its protein half-life has been measured.
Gene: Protein-coding gene on chromosome 12 (71,839,707 to 71,927,248, forward strand). Ensembl gene ENSG00000121749.
Subcellular location: Cytoplasm
Subcellular location (Human Protein Atlas): Cytosol; Mitochondria
Pathways (Reactome):
Vesicle-mediated transport: TBC/RABGAPs
Gene Ontology:
Molecular function: protein binding; GTPase activator activity
Biological process: regulation of cilium assembly; regulation of GTPase activity
Cellular component: cytosol; mitochondrion; cytoplasm; extracellular region
Genetic constraint (gnomAD): Loss-of-function variants: 20 observed, 45.9 expected, observed/expected ratio (o/e) 0.44, 90% interval 0.31 to 0.63. The upper end of that interval is the gene's LOEUF score, 0.63, which puts it in group 2 of 6, group 1 being the genes least tolerant of losing a copy. Missense variants: 484 observed, 540.51 expected, observed/expected ratio (o/e) 0.9, 90% interval 0.83 to 0.96. Synonymous variants: 176 observed, 184.29 expected, observed/expected ratio (o/e) 0.95, 90% interval 0.84 to 1.08.
Homologues: Orthologues: chimpanzee TBC1D15 (99% identical), macaque TBC1D15 (98% identical), dog TBC1D15 (96% identical), guinea pig TBC1D15 (94% identical), pig TBC1D15 (94% identical), rat Tbc1d15 (92% identical), mouse Tbc1d15 (91% identical), rabbit TBC1D15 (90% identical), tropical clawed frog tbc1d15 (70% identical), zebrafish tbc1d15 (62% identical). Paralogues in human: TBC1D17 (47% identical), TBC1D16 (16% identical), TBC1D5 (15% identical), TBC1D25 (15% identical), RABGAP1L (14% identical), TBC1D1 (14% identical), TBC1D2B (14% identical), USP6NL (14% identical), TBC1D4 (14% identical), RABGAP1 (13% identical), TBC1D10B (13% identical), TBC1D22B (13% identical), and 33 more.
Diseases named in the same sentence as TBC1D15 in open-access papers:
TBC1D15 is named in the same sentence as 33 diseases in open-access papers, as found by Europe PMC text mining. Sharing a sentence is not in itself a finding about the gene and the disease. The quoted sentences say what the papers report.
acute myocardial infarction (3 papers, 2020 to 2025). Necrosis of the myocardium, as a result of interruption of the blood supply to the area. "This study was designed to explore the role of TBC1D15 in acute myocardial infarction (MI)-induced cardiac injury and the possible mechanism(s) involved." (PMID 33042281, 2020). "Data from Evans blue/TTC staining showed that under the same degrees of AAR, TBC1D15 attenuated myocardial infarct size following 3-day MI (24.44 ± 1.99 vs. 44.52 ± 3.88 from MI, P < 0.05), the effect of which was nullified by either TBC1D15 mutant." (PMID 33042281, 2020). "Rab7a may be activated by multiple mechanisms through a GEF such as Ccz1, reducing TBC1D15 (GAP protein) levels as shown in vitro and in a mouse model of myocardial infarction, or through post-translational protein modifications." (PMID 41024170, 2025).
hepatocellular carcinoma (3 papers, 2013 to 2022). A malignant tumor that arises from hepatocytes. "We examined hepatocellular carcinoma (HCC) development in alcohol Western diet-fed hepatitis C virus NS5A Tg mice with hepatocyte-specific TBC1D15 deficiency or expression of non-phosphorylatable NUMB mutations." (PMID 32555153, 2020). "To further investigate a potential role for TBC1D15 in oncogenesis, we examined its expression in hepatocellular carcinoma (HCC) and in matched, adjacent noncancerous tissues obtained from surgically resected clinical specimens." (PMID 23468968, 2013).
Alzheimer disease (2 papers, 2019 to 2024). A progressive, neurodegenerative disease characterized by loss of function and death of nerve cells in several areas of the brain leading to loss of cognitive function such as memory and language. "TBC1D15, a Rab GTPase, plays a crucial role in lysosomal membrane repair, yet its function in regulating microglial autophagy in Alzheimer's disease remains unexplored." (PMID 39812537, 2024). "It is suggested that targeting microglial TBC1D15 may be an important strategy for enhancing autophagy, which facilitates the clearance of amyloid plaques as a therapeutic approach for Alzheimer's disease." (PMID 39812537, 2024). "Furthermore, TBC1D15 levels are significantly elevated in the lysosomes of microglia in Alzheimer's disease." (PMID 39812537, 2024).
epilepsy (2 papers, 2024). A brain disorder characterized by episodes of abnormally increased neuronal discharge resulting in transient episodes of sensory or motor neurological dysfunction, or psychic dysfunction. "However, further studies are needed to explore the specific mechanism of TBC1D15-regulated mitochondria–lysosome membrane contact and mitochondrial calcium overload in epilepsy." (PMID 39390030, 2024).
Hepatitis (2 papers, 2020 to 2024). Inflammation of the liver. "Inhibitor A suppressed the interaction between TBC1D15 and NICD, which, if left unchecked, would promote HCC growth in patients with known etiological backgrounds of alcoholism, obesity, and hepatitis." (PMID 38409448, 2024).
melanoma (2 papers, 2020 to 2022). A malignant, usually aggressive tumor composed of atypical, neoplastic melanocytes. "Seven prognosis associated TBCs genes including TBC1D13, TBC1D16, TBC1D7, TBC1D10C, TBC1D19, TBC1D8B, and TBC1D15 were identified in melanoma." (PMID 33194704, 2020).
Parkinson’s (2 papers, 2021 to 2025). "Ultimately, these defects resulted in disrupted mitochondrial distribution and function, but could be rescued by TBC1D15 in Parkinson’s patient GBA1-linked neurons." (PMID 33753743, 2021). "These defects resulted in disrupted mitochondrial distribution and function, and could be further rescued by TBC1D15 in Parkinson’s patient derived GBA1-linked neurons." (PMID 33753743, 2021). "Parkinson’s disease patient derived neurons harboring mutant GBA1 exhibited prolonged mitochondria-lysosome contacts due to defective modulation of the untethering protein TBC1D15, which mediates Rab7 GTP hydrolysis for contact untethering." (PMID 33753743, 2021). "In a study conducted in Parkinson’s patients linked to GBA1 (β-glucocerebrosidase), a lysosomal hydrolase, it was reported that there was no significant change in RAB7 total protein levels, but TBC1D15 (RAB7-GAP) levels changed." (PMID 40565173, 2025).
Type 2 diabetes (2 papers, 2015 to 2019). "The involvement of APSL at the N-terminus of TBC1D15 also demonstrates that this protein might be involved in insulin signaling and may be associated with the development of type 2 diabetes." (PMID 25984991, 2015). "Because the APSL fragment lies in the N-terminus of the shark TBC1D15 protein, we speculate that shark TBC1D15, containing the APSL fragment, may be closely associated with type 2 diabetes." (PMID 25984991, 2015).
Autoimmunity (1 paper, 2022). The occurrence of an immune reaction against the organism's own cells or tissues. "The stimulator of IFN genes mediated DNA sensing pathway plays an important role in the innate immune response to pathogen infection, autoimmunity, and cancer, which was regulated by TBC1D15, mitochondrial dynamics mediators." (PMID 35057823, 2022).
cervical carcinoma (1 paper, 2013). A carcinoma arising from either the exocervical squamous epithelium or the endocervical glandular epithelium. "Using an antibody raised against TBC1D15, we carried out reciprocal immunoprecipitations of the endogenous, untagged proteins and confirmed the interaction of Numb and TBC1D15 in two additional cell lines, PIL-4 hepatoblasts and HeLa cervical carcinoma cells." (PMID 23468968, 2013).
diabetes (1 paper, 2015). "In future studies, we intend to investigate the role of shark TBC1D15 in the regulation of diabetes by elucidating the key molecular mechanisms of this process." (PMID 25984991, 2015).
liver cancer (1 paper, 2020). An epithelial or non-epithelial malignant neoplasm that arises from the liver. "For this, the TCGA liver cancer data were analyzed for expression of TBC1D15 and NOTCH1 in relation to HCC stage." (PMID 32555153, 2020).
ovarian carcinoma (1 paper, 2024). A malignant neoplasm originating from the surface ovarian epithelium. "The TCGA database revealed poorer survival rates with higher levels of TBC1D15 mRNA expression in liver, lung, breast, and ovarian cancer patients." (PMID 38409448, 2024).
pulmonary fibrosis (1 paper, 2026). Chronic progressive interstitial lung disorder characterized by the replacement of the lung tissue by connective tissue, leading to progressive dyspnea, respiratory failure, or right heart failure. "Given that nestin promotes myofibroblast activation by recruiting TBC1D15 to inactivate Rab7 and regulating EVs secretion, we next examined the role of Rab7 in the pathogenesis of experimental pulmonary fibrosis in vivo." (PMID 41496459, 2026).
status epilepticus (1 paper, 2024). Status epilepticus is defined as a continuous seizure lasting more than 30 min, or two or more seizures without full recovery of consciousness between any of them. "Lentiviral vectors (Lv) infection and stereotaxic adeno-associated virus (AAV) injection were used to regulate TBC1D15 expression before establishing in vitro epileptiform discharge and in vivo status epilepticus (SE) models." (PMID 39390030, 2024). "TBC1D15 exerts neuroprotective effects via regulation of mitochondria–lysosome membrane contact in the PILO-induced status epilepticus rat model." (PMID 39390030, 2024).
tumor (5 papers, 2013 to 2024). "Knockout of TBC1D15, Notch1, or Notch2 alone or in combination was observed to reduce the tumor masses in these animals." (PMID 38409448, 2024). "TBC1D15 has two major tumor-promoting pathways: interference of the asymmetric division machinery by interacting with NuMA1 and disruption of NuMA1–LBN association." (PMID 32555153, 2020). "Freshly-isolated TICs transduced with shRNA lentivector were transplanted subcutaneously into NSG mice forming a growing tumor which was reduced in size by more than 80% upon TBC1D15 KD." (PMID 32555153, 2020). "In summation, our research described the molecular mechanisms of the oncogenic activity of TBC1D15 overexpressed in tumor cells and TICs." (PMID 32555153, 2020). "We sought to determine the translational relevance of the tumor promotion activity of TBC1D15 as described in the present studies." (PMID 32555153, 2020). "Conversely, N1ICD expression alone resulted in a significant increase in tumor growth promotion that was attenuated by TBC1D15 KO to the level below the growth achieved in control TICs." (PMID 32555153, 2020). "To address the generality of these findings, we carried out an extensive meta-analysis of TBC1D15 expression in a panel of tumors arising from diverse tissue types and in matching, non-tumor control tissues." (PMID 23468968, 2013). "Through this approach, we detected significant (P<0.05) increases in TBC1D15 expression in several tumor types, including those derived from breast, prostate, thyroid and nasopharyngeal tissues." (PMID 23468968, 2013). "Antagonists of TBC1D15 interactions with NICD are expected to decrease tumor incidence." (PMID 38409448, 2024). "Immunohistochemical analyses revealed increased levels of TBC1D15, NUMB, NOTCH1, and TOM20 in the tumor tissues of NSG mice injected with CD133(+) TICs." (PMID 38409448, 2024). "PIL4 cells expressing N1ICD expression formed large tumors within 2 months of transplantation, but TBC1D15 KD in these cells significantly reduced this growth, confirming that the N1ICD tumor promotion effect required TBC1D15." (PMID 32555153, 2020). "To explore the significance of TBC1D15 in TISC-mediated oncogenesis, we carried out in vivo tumor formation titration assays in which defined numbers of TISCs were implanted subcutaneously into immune-compromised NOD/Shi-scid, IL-2Rγ null (NOG) mice." (PMID 23468968, 2013). "Functional significance of the NOTCH interacting and CNO domains of TBC1D15 was shown by incrementally deletions of TBC1D15 and corresponding reduced spheroid formation or tumor growth of non-neoplastic immortalized human cell line, PH5CH31 in NSG mice." (PMID 32555153, 2020). "Quantitative scoring of stained specimens revealed that 42.8+/−7.3% of tumor cells, but only 5.2+/−0.5% of noncancerous control cells, were strongly immunopositive for TBC1D15 (P<0.01)." (PMID 23468968, 2013).
cancer (4 papers, 2019 to 2024). A tumor composed of atypical neoplastic, often pleomorphic cells that invade other tissues. "The identification of a cancer mutation within the LIR motif in TBC1D15 indicates that the disruption of TBC1D15 function in mitophagy may contribute to cancer development." (PMID 34059679, 2021). "The researchers also identified small molecules that can disrupt the TBC1D15-NOTCH1 interaction, offering a new approach to target TICs in cancer treatment." (PMID 38409448, 2024). "However, it is unknown whether TBC1D15 exerts its pro-cancer activity through mitophagy." (PMID 34059679, 2021). "The results showed that interfering with the TBC1D15-NOTCH1 interaction could reduce the growth of TICs and potentially improve cancer treatment outcomes." (PMID 38409448, 2024).
cardiovascular diseases (2 papers, 2020 to 2024). "However, more in-depth scrutiny should be engaged towards understanding the role of TBC1D15 in other pathological conditions especially for cardiovascular diseases." (PMID 33042281, 2020). "Additionally, TBC1D15 has a marked effect on cardiovascular diseases and may be a novel therapeutic target for acute myocardial infarction." (PMID 39390030, 2024).
TBC1D15 also shares sentences with these, for which no sentence is quoted: infection (3 papers); ischemia (2); acute myeloid leukemia (1); alcoholic cirrhosis (1); alcoholism (1); breast carcinoma (1); cholangiocarcinoma (1); glioblastoma (1); Hyperglycemia (1); ischemic cardiomyopathy (1); lung carcinoma (1); neurological disorders (1); Obesity (1); schizophrenia (1); skin cutaneous melanoma (1).